PPARG (peroxisome proliferator activated receptor gamma)
Diseases named in the same sentence as PPARG in open-access papers (continued):
Sharing a sentence is not in itself a finding about the gene and the disease.
cancer (continued). "Notably, the RXRA protein was in protein complexes with RARA, PPARG, NCOA1, NCOA2, and NCOR2 cancer drivers." (PMID 29572294, 2018). "Therefore, each of the molecular interactions of PPARγ and PGC-1α with other transcriptional partners needs to be further investigated to understand the role of PPARγ and PGC-1α in cancer." (PMID 29599799, 2018). "Although the PPARG agonists rosiglitazone and pioglitazone are not used in the clinic, those agonists can suppress cancer cell proliferation." (PMID 29765046, 2018). "The differentiation into adipocyte-like cells and triglycerides accumulation upon DEX exposure may be thus due to the consequence of higher PPARγ expression in A-549 and MCF-7 cancer cells." (PMID 30460096, 2018). "By docking analysis, they observed that anti-cancer fatty-acid derivative, called AIC-47, was able to bind PPARγ, making it transcriptionally active, and indirectly reducing c-Myc protein levels, since PPARγ activation is related to the proteasome degradation of β-catenin, as already mentioned." (PMID 29966227, 2018). "Its expression was found in several human cancer cell lines and multiple human tissues, and not in endothelial cells, but is—surprisingly—induced by PPARγ." (PMID 27699500, 2017). "It is also known that PPARγ can regulate AMPK and eNOS signaling, which in our system using pemetrexed and sildenafil could be a point of convergence for the observed anti-cancer effects of both drugs." (PMID 27903966, 2017). "Recent studies have demonstrated that the endogenously produced peroxisome proliferator-activated receptor gamma (PPARγ) antagonist cyclic phosphatidic acid (cPA), which is structurally similar to LPA, inhibits cancer cell invasion and metastasis in vitro and in vivo." (PMID 29258184, 2017). "Interestingly, cancer immunity-related cytokine and antigen processing/presentation pathways were commonly downregulated in MIBC bearing RXRA or PPARG alterations." (PMID 28740126, 2017). "Surprisingly, unlike classic oncogenic pathways that promote cancer cell proliferation, PPARγ/RXRα alterations slightly reduced cell growth in vitro." (PMID 28740126, 2017). "Previously, there have not been studies examining the interaction of PP5 with PPARγ in bladder epithelium and cancer development." (PMID 28348577, 2017). "It is also noteworthy that UHRF1 regulates a plethora of other TSGs among which RB1 especially in Jurkat and osteosarcoma cells, CDX2, CDKN2A, RUNX3, FOXO4, PPARG, BRCA1 and PLM, in gastric cancer, SOCS3 and 3OST2 in endometrial carcinoma as well as BRCA1 in cancer breast cell lines." (PMID 27839516, 2016). "In addition, the rest of 11 TFs such as SAMD4, MYC, PPARG, and PPARA have also been proved to play key roles in various cancer progressions." (PMID 26425543, 2015). "In relation with silencing the expression of PPARG by molecular tools, our results show that the proliferation rate of RNAi-PPARG MCF-7 cells was two-fold greater than that of MCF-7 control cells, corroborating similar reports in other cancer cells." (PMID 26376791, 2015). "In addition, the rest of TFs such as PPARG, PPARA, SMAD3, MYC, and STAT1 have been proved to be related to cancer progression." (PMID 26425543, 2015). "Also, PPARγ, in HER2-positive cancer cells, which produce high levels of endogenous fat, helps to convert FAs to triglycerides, thus allowing these cells to avert the cell death resulting from endogenous palmitate-related lipotoxicity." (PMID 23431283, 2013). "The search for genetic alterations for the identification of malignancy has low sensitivity, since numerous cancer samples do not bear any of these genetic alterations, and low specificity, since benign adenoma shares genetic lesions (RAS, PPARg and RET/PTC) with cancer." (PMID 23946782, 2013).
cancer (continued). "Moreover, 2,3-cyclic phosphatidic acid, an endogenously produced PPARγ antagonist, that is similar in structure to LPA, inhibits cancer cell invasion and metastasis in vitro and in vivo." (PMID 23467751, 2013). "For example, 15d-PGJ2 exerts inhibitory effect against cancer cell proliferation both with and without subjecting to PPARγ activation." (PMID 23213321, 2012). "In vitro and in vivo studies have demonstrated antiproliferative and proapoptotic actions of PPARγ agonists such as 15d-PGJ2 and thiazolidinediones (TZDs) thus suggesting that PPARγ could be a promising therapeutical target for the treatment of cancer." (PMID 23213321, 2012). "A novel high-affinity PPARγ agonist, and thiazolidinedione derivative, RS5444, demonstrated additive antiproliferative activity on DRO90-1 and ARO81 anaplastic thyroid carcinoma cells, a particularly aggressive and dedifferentiated cancer." (PMID 22966225, 2012). "Finally, PPARγ hampers the Epithelial–mesenchymal transition (EMT), a well-known process that allows cancer cells to acquire invasive ability, a prerequisite for metastasis formation." (PMID 22848209, 2012). "In some, but not all, cancer cells, TTA inhibits cancer cell growth via increased lipid peroxidation and oxidative stress, or partly via activation of peroxisome proliferator activated receptor gamma." (PMID 22027281, 2011). "PPARγ signaling is connected to the inhibition of inflammatory markers (COX-2, cytokines, and inducible nitric oxide synthase), PI3K/Akt pathway, and angiogenesis while inducing CDK inhibitors, differentiation and apoptosis markers in cancers." (PMID 22254089, 2011). "This indicates either that PPARγ activity is not related to risk of ACS, or that the activation of target genes in relation to risk of ACS is different than for cancer." (PMID 19500413, 2009). "This review summarizes studies relating PUFAs to PPARγ and cancer and offers a new paradigm relating an n-3 PUFA through PPARγ to the expression of the cell surface proteoglycan, syndecan-1, and to the death of cancer cells." (PMID 18769551, 2008). "PPARγ appears to be expressed in most if not allbreast cancer cell lines, as well as in normal and malignant breast tissue." (PMID 19125177, 2008). "Thus, one assumes that there are directtranscriptional targets, where PPARγ, in combination with the RXR receptor, binds to regulatoryelements and induced transcription.These targets have been difficult to identify in cancer cells." (PMID 18509496, 2008). "4-OH-, and 4-oxo-DHA, while not yet shown to bemade by cancer cells, also activate PPARγ with greater potency (ED50'sof 13.4 and 7.8 μM inactivating a cellular PPARγreporter, resp)." (PMID 18769551, 2008). "In cancer model systems, someeffects of PPARγ agonists were not inhibited by PPARγ antagonists,suggesting noncanonical or PPARγ-independent mechanisms." (PMID 18779871, 2008). "Theconsequences of POX induction and its role in PPARγ-mediatedmetabolic effects other than that on cancer have not been explored." (PMID 18670615, 2008). "Adjuvant therapy using PPARγ agonists may, bystimulating PPARγ-dependent downregulation of CXCR4 on cancer cells, slow the rate of metastasis and impact beneficially ondisease progression." (PMID 18779872, 2008). "Although PPARγ was not a target for EPA in breast andprostate cancer cells, a recent report has demonstrated that EPA was aneffective PPARγ transactivator in HT-29 human coloncancer cells." (PMID 18769551, 2008). "PPARγ constitutes the most extensively studied of the three PPAR subtypes (α, β, γ) since its function relates to lipid metabolism as well as cell differentiation, apoptosis and cancer." (PMID 17767717, 2007). "In contrast, 10 of the 12 carcinomas lacked PPARγ protein and PPARγ protein was detected in only two carcinomas." (PMID 15266333, 2004).
cancer (continued). "The level of PPARγ protein was below the measurement sensitivity in all of the eight carcinomas in which COX-2 protein was detected, whereas COX-2 protein lacked in the two carcinomas in which PPARγ protein was detected." (PMID 15266333, 2004). "However, at 10 μM, we observed a modest reduction in proliferation, probably due to non-specific cytotoxicity rather than targeted inhibition of PPARG, as previously reported in other cell types (e.g. adipocytes and cancer cells)." (PMID 40705926, 2025). "PPARγ exerts its anti−inflammatory influence via transrepression of NF−κB and STAT3, two master regulators of inflammatory gene expression, and the modulation of their interaction appears necessary to suppress white adipose tissue inflammation in the context of cancer cachexia." (PMID 41476922, 2025). "Although these latter studies were not conducted in the context of cancer cachexia, they further support the concept that PPARγ activation may mitigate metabolic stress and preserve skeletal muscle integrity." (PMID 41476922, 2025). "Consequently, targeting PPARG and PTEN-PI3K/AKT could hold great potential for enhancing chemotherapy efficacy across different cancer types, warranting further investigation in cancer therapy." (PMID 38505269, 2024). "According to the TCGA pan-cancer cohort, there were no significant prognostic differences between the high PPARG regulon and low PPARG regulon based on univariable Cox regression analysis, indicating that the PPARG regulon was not a purely prognostic indicator." (PMID 38773508, 2024). "Our experimental data analysis results are supported by our pathway analysis, which reveals that PPARG interacts with part of the key players in the PTEN-PI3K/AKT pathway to regulate the normal tissue microenvironment, thus influencing chemosensitivity in cancers." (PMID 38505269, 2024). "In adipocytes, EVs from cancer cells contain miRNA-155, which promotes beige/brown differentiation and remodels metabolism in resident adipocytes by downregulating PPARγ expression but does not significantly affect biological conversion to C2C12 (myoblast cell line)." (PMID 37047783, 2023). "However, another study indicated that PPARγ-mediated upregulation of phosphatase and tensin homolog (PTEN) resulted in the inhibition of PI3K signalling, thus reducing the self-renewal and aggressiveness of cancer stem cells." (PMID 35328822, 2022). "It is important to note that the anti-cancer effects of thiazolidinediones (rosiglitazone, pioglitazone, and troglitazone) might be independent of PPARγ activation, as it has been demonstrated that they are mediated by translation inhibition." (PMID 35954274, 2022). "In addition to PPARγ, other receptors including the related PPARβ/δ and estrogen-related receptor α, and signaling involving VEGF are also known to increase the metastatic potential of cancer." (PMID 35445019, 2022). "Moreover, the expression of PPARγ and DNMT1 was found to be dysregulated in various cancers." (PMID 34439147, 2021). "Furthermore, after the blockade of PPARγ/SOD2 pathway, ATG4D was located in mitochondria to activate the process of mitophagy, contributing to the increase of mitochondrial ROS production, damage of MMP stabilization and promotion of cancer cell apoptosis." (PMID 35186942, 2021). "Thus, the activation of PPARγ metabolically reprograms CAFs to favor autophagic and glycolytic behaviors, allowing cancer cells to use nutrients from non-autonomous sources to sustain their uncontrolled proliferation and other activities." (PMID 33946986, 2021). "Overall, our results point to a PPARγ-driven pro-tumorigenic role of ILC2s in IL-33-dependent tumors and suggest that PPARγ targeting in ILCs may become an attractive add-on therapy for ILC2-driven diseases, including cancer." (PMID 33953160, 2021). "Genetically modified mice in which macrophages could not express the PPARγ protein and thus not produce Grp132 displayed less inflammation, and cancer growth was blocked." (PMID 33352766, 2020).
cancer (continued). "Furthermore, high PPARG expression was found to have a protective effect in five cancer types, e.g. BLCA (HR = 0.5, 95% CI 0.35–0.7, P = 6.7e-05), and an adverse effect in seven cancer types, e.g. LIHC (HR = 2.18, 95% CI 1.51–3.14, P = 2e-05)." (PMID 32024906, 2020). "Thus, most review papers come to no consistent conclusion about the clinical use of PPARγ agonists for cancer treatment." (PMID 30424016, 2018). "However, most of the reported actions of PGC-1α in cancer were not related to the expression of PPARγ." (PMID 29599799, 2018). "PPARγ stimulation may kill cancer cells without toxicity to normal cells, such as astrocytes, and their effects are additive with other cytotoxic agents." (PMID 30405366, 2018). "More broadly, the ability of LATS2 to modulate master regulators of lipid metabolism such as PPARγ and SREBP expands the functional consequences of the deregulation of Hippo pathway components in cancer and may indicate a metabolic Achilles' heel of particular tumors." (PMID 30456386, 2018). "However, the expression and the roles of PGC-1α in cancer were not significantly related to the expression of PPARγ." (PMID 29599799, 2018). "In contrast to accelerated ROS production at complex III of the mitochondrial electron transport chain upon acute exposure of cells to hypoxic conditions, the HIF-1/PPARγ/UCP2 pathway defined here may represent a long-term mode of ROS regulation and maintenance in hypoxic carcinomas." (PMID 28042952, 2017). "Furthermore, by using the dominant-negative PPARγ (dnPPARγ) myeloid-specific overexpression bitransgenic mouse model, we found that PPARγ plays a key role in controlling pro-inflammatory cytokine synthesis, MDSC expansion, immunosuppression, and the development of cancer." (PMID 26625314, 2016). "However, other studies have shown that treatment with the PPARγ agonist rosiglitazone and troglitazone, or conversely with PPARγ antagonists GW9662 and T0070907, were both found to significantly inhibit the growth of a wide variety of cancer cell lines." (PMID 23431460, 2013). "Currently both clinically approved TZDs, rosiglitazone and pioglitazone, undergo critical evaluation of their clinical use due to adverse cardiovascular, cancer and skeletal effects, nonetheless there is no doubt that PPARγ agonists are the most effective among available anti-diabetic drugs." (PMID 23272157, 2012). "The effect of PPARγ agonists on cellular apoptosis is also variable, with increased apoptosis in some cancer cells and none in others, which might be due to modulation of the signaling molecules by PPARγ ligands in various cancer pathways." (PMID 21144036, 2010). "Thiazolidinedionesor other PPARγ ligands may have efficacy during early stagesof cancer development, by targeting carcinogenesis prior to onset of initiatingevents that are no longer subject to PPARγ repression." (PMID 19125177, 2008). "Indeed, PPARγ agonists including anti-diabetic agents, polyunsaturated fatty acids as well as non-steroidal anti-inflammatory drugs (NSAID) have been demonstrated to affect proliferation and differentiation in cancer cell lines." (PMID 17767717, 2007). "In addition, studies utilising the irreversible PPARγ-selective antagonist GW9662, have revealed PPARγ-dependent and -independent mechanisms of growth inhibition, further highlighting the incongruity of responsiveness between cancer types." (PMID 16519808, 2006). "The downregulation of the key adipogenic factors (C/EBPβ, C/EBPα, PPARγ and SREBP-1c) together with the repression of lipogenic factors (ACC, FAS, SCD-1, GPAT and Glut-4) suggests that impairment in the formation and lipid storing capacity of adipose tissue occurs in cancer cachexia." (PMID 17047651, 2006). "In addition, although most of the known target genes activated by PPARγ belong to the pathway of metabolism and lipid transport, the target genes mediating the pro- or anti-cancer activity by affect of the activated PPARγ have not yet been identified." (PMID 16854216, 2006).
cancer (continued). "Interestingly, PPARγ agonism has been shown to alter cancer derived EV-miRNAs, but it is not known whether pioglitazone treatment in people with T2D exerts any pharmacologic effect via regulation of AT-derived EV-miRNAs." (PMID 36120427, 2022). "As the canonical Wnt/β-catenin signaling pathway plays a crucial role in the development of cancer through chronic inflammation, non-steroidal anti-inflammatory drugs, such as PPARγ agonists, might serve as potent therapeutic agents to treat cancers as they inhibit the Wnt/β-catenin pathway." (PMID 33863923, 2021). "Besides, it can be observed that both PPARγ antagonist treatment and PPARγ knockdown did not cancel the anti-cancer effect of HSYA totally, suggesting the involvement of other pathways in the HSYA-mediated CRC inhibition, which need to be clarified in the future research." (PMID 34889713, 2021). "Thus PPARγ may no longer be able to upregulate the down-stream cancer-promoting genes, such as VEGF, and to suppress those genes connected to apoptosis." (PMID 31258834, 2019). "Therefore, as a limitation in this study, it was difficult to conclude whether the anti-cancer effect of PPARγ activation was dependent on PTEN without gene-knockout validations." (PMID 30845932, 2019). "Thus, this review focuses on the role of PGC-1α, independent of the role of PPARγ in cancer." (PMID 29599799, 2018). "Thus PPARγ may no longer be able to upregulate the down-stream cancer-promoting genes, such as VEGF, and to suppress apoptosis." (PMID 28415688, 2017). "Furthermore, PPARγ induced mammary cell differentiation, which is also accompanied by enhanced maspin expression; however, it is not known if PPARγ directly regulates maspin expression in cancer cells." (PMID 24034496, 2013). "In HCC, it is not clear whether PPARγ promotes cancer or can control it." (PMID 23316217, 2012). "The expression levels of EP400, HMGB2, CDK1, PPARG, and MVK were found to be significantly correlated with HMGA1 expression level in both analyzed cancer subtypes but not in non-cancerous tissue of the lung." (PMID 35805937, 2022). "The results clearly demonstrate that low expression of ACOX2 in cancer cells significantly inhibits the expression of PPARA, but not PPARD and PPARG." (PMID 33414412, 2021). "It is important to note that CBD antitumor properties in other types of cancer have not been related to dual CB1R and PPARγ." (PMID 33498245, 2021). "This disparity may be due to the higher percentage of cancer documented in American RAS-mutated indeterminate nodules, possibly because the Bethesda and SIAPEC classifications do not perfectly overlap, and/or because our panel did not include RET/PTC and PAX8/PPARG rearrangement analysis." (PMID 29085338, 2017). "The genotype frequencies of PPARG rs1801282 C>G were 93.21% (CC), 6.53% (CG) and 0.26% (GG) in CRC patients, which were not significantly different from those in non-cancer controls (90.28% CC, 9.39% CG and 0.33% GG)." (PMID 29246001, 2017). "Moreover, previous studies heavily relied on the usage of PPARγ ligands, which may exert PPARγ-independent and/or physiologically irrelevant effects; whereas in vivo genetic dissection of the specific PPARγ functions in each cell type in the cancer milieu is lacking." (PMID 27692066, 2016). "No changes were observed in PPARγ mRNA expression while the expression of PPARδ, retinoid-activated receptors and COX-2 were significantly increased in cancer tissues compared to normal colon mucosa (P ≤ 0.001)." (PMID 17767717, 2007). "Although PPAR isoforms have been previously related to cancer progression and some studies considered PPAR as a negative prognostic marker, surprisingly, PPARG is down-regulated in human skin cutaneous melanoma (SKCM) in comparison to corresponding normal tissue." (PMID 36834531, 2023). "However, the DIM-Ph-4-X signaling pathways for cancer cell inhibition were observed to be both dependent and independent of NR4A1 and PPARγ interaction." (PMID 29861853, 2018).